GFAP (glial fibrillary acidic protein)
Diseases named in the same sentence as GFAP in open-access papers (continued):
Sharing a sentence is not in itself a finding about the gene and the disease.
tumor (continued). "Analogously to tumors induced in wild-type mice, those induced in NG2-KOs did not express the astrocytic marker GFAP, even if GFAP-positive reactive astrocytes were frequently abundant within tumor masses." (PMID 20939912, 2010). "Immunohistochemically, the tumour cells express vimentin, desmin, smooth muscle actin, and muscle specific actin, but not cytokeratin, neurofilament, or glial fibrillary acidic protein." (PMID 19068127, 2008). "The tumor cells were negative for S-100, glial fibrillary acidic protein (GFAP), cytokeratin AE1/AE3 keratin, anti-cytokeratin (CAM 5.2) and chromogranin." (PMID 18817561, 2008). "The tumour cells expressed S-100 protein and glial fibrillary acidic protein (GFAP) and were negative for HMB45, melan A, smooth muscle actin (SMA), desmin, CD34 and CD117." (PMID 18518995, 2008). "The presence of both neurons and astroglia cells, respectively, within the tumours has been verified by immunofluorescence using antibodies against MAP2 and GFAP, which confirmed the observation of the reduced numbers of both types of cells in the transchromosomic tumours, compared to controls." (PMID 18047653, 2007). "GFAP-positive cells within ganglia of the plexus could also be found in tumor areas but were not included in our analysis." (PMID 40580485, 2025). "The excised tumor tissue was sent to a board-certified pathologist for histopathological analysis and additional immunohistochemistry (IHC) testing, including markers for cytokeratin AE1/AE3, vimentin, oligodendrocyte transcription factor 2 (Olig2), and glial fibrillary acidic protein (GFAP)." (PMID 40362055, 2025). "The tumor was difficult to diagnose, exhibiting GFAP and SOX10 negative and MAP2 positive." (PMID 41331048, 2025). "Moreover, in our study cohort, GFAP immunohistochemistry suggested a better survival for patients with high-density staining independent of known established prognostic factors such as TNM stage and tumor differentiation." (PMID 40580485, 2025). "Tumor cells are GFAP-positive but negative for OLIG2 and neuronal markers." (PMID 38544524, 2024). "Loss- and gain-of-function combined with scRNA-seq reveal that tumor cells with higher levels of ASCL1 relative to OLIG2, as seen in the Olig2-CKO and Ascl1-OE tumors, favor activation of a NSC/astrocyte program, characterized by high expression of GFAP and a highly migratory or diffuse phenotype." (PMID 39609428, 2024). "While areas of the PLAGL1 amplified tumor showed strong positivity for GFAP or synaptophysin, sometimes with overlapping areas of staining, other areas of the tumor were largely negative for both lineage markers with small clusters or occasional cells showing positivity." (PMID 39228008, 2024). "Olig2 and synaptophysin IHC were positive in the tumor cells while GFAP was mostly negative." (PMID 39409964, 2024). "The tumour cells are positive for OLIG2 and synaptophysin but may lack GFAP." (PMID 39294363, 2024). "The tumor cells typically test positive for GFAP and negative for Olig2." (PMID 38137148, 2023). "Notably, this approach did not reduce the total number of PSCs in the tumor, as levels of the fibroblast marker, glial fibrillary acidic protein (GFAP), remained unchanged." (PMID 37345116, 2023). "A few entrapped or reactive astrocytes expressed GFAP, but the tumor cells were negative." (PMID 35663322, 2022). "Indeed, we found that the most striking OATP expression occurred within the bulk tumor parenchyma, this was reinforced by a positive correlation of all OATPs with GFAP immunoreactivity in GBM tissue, but not in non-tumor brain tissue." (PMID 36382105, 2022). "Therefore, even though serum GFAP is not always a reliable predictor of tumour volume, it is, beyond this exception, a good measure of BBB breakdown and necrosis." (PMID 35919979, 2022).
tumor (continued). "Using the Kaplan–Meier survival curves and log-rank tests, we compared the estimates of clinical outcomes among different molecular subtypes, tumor location, involvement of dominant versus non-dominant cerebral hemisphere, extent of ablation, GFAP staining, and Ki67 index level." (PMID 36359474, 2022). "GFAP staining was very low in the original tumor tissue, and absent in the 3D cultures and whereas MIB-1 signal strength was low, similar to that observed in the tumor tissue indicating that the spheroids recapitulated the mixed cell lineage and marker expression seen in the tumor." (PMID 35370679, 2022). "However, it should be noted that dynamic measurements will not improve false negatives in cases where tumours have low serum GFAP, due to low GFAP expression." (PMID 35919979, 2022). "On univariate analyses, longer overall survival was also associated with older age (> 3 years) and positive ASCL1 staining, but not OLIG2 or GFAP staining, tumor location, gross total resection or the presence of pathogenic/likely pathogenic SMARCB1 germline variants." (PMID 35501487, 2022). "Moreover, although we did find a positive correlation between GFAP expression and tumor dimension, it was not statistically significant." (PMID 36359474, 2022). "Negative GFAP staining in embryonal appearing tumor cells was shown for 84% (21/25) of cases." (PMID 33876327, 2021). "When the tumor sizes were compared, the differences among the six groups were not significantly different and IHC examination of stem cell (Nestin), neural (MAP2), glial (GFAP), cell proliferation (Ki67), and mitochondrial markers failed to reveal major differences as well." (PMID 34719887, 2021). "In the tumor cells, GFAP and CD44 expression were not recovered under SS or TMZ treatments." (PMID 34638987, 2021). "Higher Olig2 and GFAP/MCM2 densities in FCD3b may reflect margins of the tumour infiltration zone rather than true cortical dysplasia." (PMID 33370704, 2021). "Copy-number profiles of GFAP positive and negative tumor parts were mostly congruent." (PMID 33876327, 2021). "It has been shown that GFAP+ and GLAST+ astrocytes, when transformed, give rise to GBM with different features: GFAP+ tumor cells are intrinsically more proliferative than GLAST-derived tumors that, instead, may rely more on the TME, as suggested by enhanced recruitment of non-malignant glial cells." (PMID 34690699, 2021). "Interestingly, the YFP+ tumor cells colocalized extensively with PDGFRα but not with GFAP or the neuronal marker NEUN." (PMID 32573857, 2020). "However, almost no GFAP mRNA was found in the tumor, whereas heterogeneous GFAP expression was observed inside the tumor by immunohistochemistry at PID21." (PMID 32977526, 2020). "Indeed, GFAP positive cells distributed around GFP-GSCs whereas IBA1 positive cells were found among GFP-GSCs, probably due to the different role and interaction with tumor cells of astrocytes and microglia." (PMID 32290386, 2020). "We hypothesize that the strong negative correlation could be due to different “strategical focuses” of the tumor cells with strong expression of EGFR in areas of cell proliferation and the strong expression of GFAP in areas of tumor invasion, as proposed before." (PMID 33066251, 2020). "As gut inflammation is known to accelerate tumor growth in the AOM/DSS model, and enteric glia can secrete and respond to inflammatory mediators, we investigated whether the GFAP+ enteric glia could be promoting tumor development by exacerbating intestinal inflammation." (PMID 33282743, 2020). "By immunohistochemistry, the tumor cells stained positively for S-100 (focal +), CD34 (strong +++), and Ki-67 (20%), and negatively for smooth muscle actin, pan-cytokeratin (CK), neurofilament (NF), pan-cytokeratin-L, GFAP, CD31, STAT6, ERG, myogenin, and MyoD1." (PMID 32590748, 2020).
tumor (continued). "Neither of the tumor cell markers glial fibrillary acidic protein (GFAP) and Olig2 was detected." (PMID 31329636, 2019). "Additionally, we found colocalization of integrin α10β1 and the astrocyte marker GFAP (Glial fibrillary acidic protein) (10‒30%) on the tumor cells but no colocalization with the pericyte marker NG2 (Neural/Glial Antigen 2)." (PMID 31027305, 2019). "Additionally, in the tumor tissues generated by co-injection the number of dedifferentiated cells expressing OCT4, GFP, and Nestin was increased, whereas the number of cells expressing the differentiated astrocyte marker GFAP was decreased." (PMID 30804471, 2019). "GFAP-positive reactive astrocytes and enhanced Cx43 expression were present at the peritumoral zone with infiltrating cancer cells, but absent in the necrotic tumor core." (PMID 31634381, 2019). "The tumor was negative for glial fibrillary acidic protein (GFAP), Wilms tumor 1 (WT1), myo-D1, myogenin, smooth muscle actin, nonphosphorylated and phosphorylated neurofilament protein, CD34, CD31, HMB-45, S-100, leukocyte common antigen, and BAF47/INI-1 (retained nuclear positivity)." (PMID 31372595, 2018). "In fact, according to our in vivo results, the GFAP/CD133+CD90+/CD44+ cells maybe the cell population responsible for EPN dissemination, leading to reduced patient survival due to the inherent chemoresistance of this tumor." (PMID 29774098, 2018). "The distinction between reactive astrocytes and tumor cells is not easy: the finding of a GFAP+ cell in mitosis does not rule out the possibility that it could be a reactive astrocyte." (PMID 30577488, 2018). "Therefore, we propose that GFAP/CD90+/CD44+ EPN cells correlate with the expression of CD133, nestin, CXCR4 and SSEA-3, which could act as markers of enrichment for tumor-initiating cells." (PMID 29774098, 2018). "However, although almost all the patients showed tumor progression or died, only a minimal GFAP increase was found and only in one patient, thus suggesting that GFAP is not predictive for tumor recurrence." (PMID 29261132, 2017). "In addition, an Ingenuity Pathway Analysis of annotations and function in physiology and pathology with a focus on cancer, indicated a significant role of GFAP-isoform regulated genes in tumour invasion (data not shown)." (PMID 29152145, 2017). "Subsequent IHC examination revealed reactive astrocytes with strong GFAP positivity surrounding the needle track but did not detect human cells in mouse brains using human-specific MT antibodies, further confirming the lack of xenograft tumor formation." (PMID 29152094, 2017). "As previously detailed, our primary cell cultures were negative for markers of hematopoietic cells (CD45), tumor-associated macrophages (CD163), activated hepatic stellate cells (GFAP), endothelial cells (CD31), fibroblast-activation protein (FAP), and stromal-derived factor (SDF1)." (PMID 28873435, 2017). "Additionally, UAS:YAPS5A promoted aggressiveness of the developing tumours characterised by strong proliferation and fast dedifferentiation, as determined by strong staining for GFAP and nearly complete lack of HU-C staining." (PMID 27935819, 2017). "Indeed, necrotic and peri-necrotic zones (associated with low pH environments) in glioblastoma patient samples showed extensive GM3 and GFAP colocalization and supraclustering, which was not seen in the non-necrotic zones of the tumor mass (see R values)." (PMID 28299282, 2017). "In contrast to R2, GFAP is present in only some but not all tumor cells." (PMID 29267253, 2017). "Meanwhile, other markers (for example, GFAP) were not present in the overall tumor tissue." (PMID 29267253, 2017).
tumor (continued). "Thus, 10 cases of carcinoma metastasis with uniformly Sox2-immunopositive nuclei for which double-labeling for Sox2 and a tumor-specific marker was not performed were used for Sox2/GFAP double-labeling." (PMID 25713758, 2015). "Cells isolated from the SEZ were found to express increased levels of glial fibrillary acidic protein (GFAP) and the angiogenesis marker CD31 when compared to cells from the tumor bulk, which supports the idea that these cells may have greater replicative potential." (PMID 26636033, 2015). "Furthermore, immunohistochemical staining showed that the tumor cells were synaptophysin- and NeuN-positive and GFAP-negative." (PMID 26376790, 2015). "Interestingly, the primary tumor of BC-P007 xenograft at the site of injection expressed collagen type II (50% moderate staining, data not shown), but not nestin, βIII-tublin and GFAP." (PMID 24670249, 2014). "As expected, we observed GFAP+ cells displaying a palisade-like arrangement in contrast to stellate astrocytes, which were distributed in the contralateral hemisphere and not in the tumor area." (PMID 25482099, 2014). "The tumor is positive for myogenic markers, not diffusely positive for S-100 and negative for GFAP." (PMID 24396458, 2014). "In addition, clinical tumor specimens of patients BC007, BC107, BC515 and BC877 were also found to express nestin (approximately 20 to 80%), βIII-tublin (approximately <10 to 35%) and approximately GFAP (35 to 80%)." (PMID 24670249, 2014). "Additionally, a negative relationship was noted between the DcR3 level and GFAP expression (r = −0.489, P < 0.01), which further indicated the correlation between DcR3 expression and tumor cell differentiation." (PMID 24741354, 2014). "The tumor cells immunolabeled with GFAP and IDH1, and were negative for EGFR." (PMID 24252196, 2013). "Slides of the tumor excised in 1992 also showed a similar morphology and a similar reaction pattern, with a slightly lower proliferation rate as compared to 2007, and a negative immunoreaction for GFAP (not shown)." (PMID 23840986, 2013). "We therefore used FACS analysis to determine whether GFAP-expressing cells were derived from tumor cells or the non-neoplastic microenvironment." (PMID 22393407, 2012). "Mouse nestin-positive blood vessels in the tumor were GFAP-negative (inset)." (PMID 22539956, 2012). "Neither tumor type stained positive for the marker of astrocytic differentiation, GFAP." (PMID 20520772, 2010). "Similarly, a proportion of SHH-1A and SHH-1B cases showed positive staining for GFAP [7/22 (32%) and 3/12 (25%), respectively], whereas positive GFAP staining (> 5% of tumor cells) was not encountered in any SHH-2 examined [0/18 (0%); Chi-Square: 6.787; df: 2; P = 0.034]." (PMID 35501487, 2022). "In order to investigate whether BET inhibition affects the tumor-initiating ability of EPN SC cultures, we assessed the expression of previously defined neural cancer SC markers (PROM1, NES and SOX2) and of the astrocytic marker GFAP in the cells treated with OTX015." (PMID 33668642, 2021). "Immunohistochemically, the tumor cells were positive for vimentin, epithelial membrane antigen, calponin, and were partially mild to moderate positive for estrogen receptor, but completely negative for S100 protein, glial fibrillary acidic protein, CD34, desmin, SMA and cytokeratin." (PMID 31915021, 2020). "A mature astrocytic differentiation of tumor cells (indicated by GFAP) could not be detected." (PMID 26883117, 2016). "The GFAP-CreER driver line allows for widespread and unbiased genetic manipulation in mature astrocytes and progenitor cells from all regions of the central nervous system and has revealed tumor formation in non-proliferative zones such as the cortex, brain stem, cerebellum and spinal cord." (PMID 22287481, 2012).
tumor (continued). "In addition, neither GFAP nor FGF3, two established astrocyte markers are associated with survival, indicating that these correlations are specific to gene expression, rather than a simple indication of astrocyte density present in the tumor microenvironment." (PMID 22393407, 2012). "These tumours frequently show expression of TTF-1 (a transcription factor most often detected in tissues of pulmonary or thyroidal origin), absence of GFAP expression and propensity for leptomeningeal spread." (PMID 39899075, 2025). "Immunohistochemical testing was performed, revealing the neoplasm was positive for Chromatogranin A, Synaptophysin and Cytokeratin AE1/AE3 and negative for Epithelial Membrane Antigen (EMA) and Glial Fibrillary Acidic Protein (GFAP)." (PMID 41025034, 2025). "The tumor was negative for cytokeratin AE1/AE3, p63, desmin, CD34, S100, glial fibrillary acidic protein (GFAP), and SOX10." (PMID 40766037, 2025). "Immunohistological examination showed that the tumor cells were positive for EMA and negative for cytokeratin AE1/AE3, p63, desmin, CD34, S100, GFAP, and SOX10." (PMID 40766037, 2025). "Significant increases in gene expression of GFAP (4-fold), a type III intermediate filament in astrocytes, and IDH1 (5-fold) were observed in tumour samples, with no observed changes in IDH2 expression." (PMID 41034696, 2025). "Some zones were negative for both GFAP and EMA, representing undifferentiated or progenitor-like tumor cells, more pronounced in ST-ZFTA tumors." (PMID 41464145, 2025). "GFAP and OLIG2 were not expressed in the sarcomatous regions of the tumor but positive within the glial component." (PMID 39707480, 2024). "Immunohistochemistry of the tumour cells was diffusely positive for CD34 and epithelial membrane antigen (EMA) and negative for glial fibrillary acidic protein (GFAP)." (PMID 38628267, 2024). "Whereas tumor cell nuclei are negative for ATRX and possibly surrounded by GFAP, the nuclei of astrocytes are positive for ATRX and also surrounded by GFAP." (PMID 38263411, 2024). "Immunostaining for markers of glial differentiation (GFAP and OLIG2) was mostly negative, with only a few PLAGL2-amplified tumors showing labeling of rare scattered tumor cells." (PMID 36437415, 2023). "Tumor cells were predominantly negative for OLIG2 and synaptophysin, positive for GFAP and demonstrated intracytoplasmic dot-like EMA staining." (PMID 36937401, 2023). "In the present case, IHC examination of the tumor revealed that vimentin was positively stained, P63, KRT14, S-100 was focally positive, Ki-67(80%), while KRT5/6, KRT7, GFAP, calponin, SMA, KRT-PAN, SOX10, mammaglobin was negative." (PMID 37705036, 2023). "Under the serum‐free microfluidic tumor‐on‐chip model, GB3‐RFP cells expressed Nestin, the neural progenitor cell marker, but not GFAP, or AQP4, suggesting that GB3‐RFP cells retained their stem properties during invasion (Figure 3biii)." (PMID 35619544, 2022). "GFAP and OLIG2 were positive in all primary tumors (10/10) with one tumor showing a mixture of positive and negative cells whereas all others showed widespread positivity." (PMID 34967922, 2022). "In combination with the results of the double immunofluorescence with GFAP and Iba1, we furthermore provide intriguing evidence that ferroptosis is more likely to take place in GBM tumor cells and not in the surrounding microglia cells." (PMID 35530303, 2022). "By immunohistochemistry (IHC), tumor cells were diffusely positive for vimentin, variably for synaptophysin, S-100, and NSE, and focally for NeuN; they were negative for GFAP and CK AE1/AE3." (PMID 36090160, 2022). "Immunohistochemistry demonstrated focal positivity of tumor cells for S100, cytokeratin AE1/AE3 and EMA, whereas GFAP was negative." (PMID 34816314, 2022). "Vascular‐like structures were detected within the tumors and they were GFAP+, but CD34‐, suggesting that they were formed by tumor cells, but not from vascular endothelial cells." (PMID 34213079, 2021).